ALB (albumin)
Diseases named in the same sentence as ALB in open-access papers (continued):
Sharing a sentence is not in itself a finding about the gene and the disease.
Hypoalbuminemia (continued). "The most consistent significant association explored in the literature was between low albumin and survival, with 74% of studies exploring this association reporting a significant relationship between hypoalbuminemia and either shorter survival or increased mortality." (PMID 40103850, 2025). "Hypoalbuminemia (low levels of albumin) detected within the blood can be associated with liver failure, but as homeostasis of albumin requires only a partially functioning liver, this association typically occurs during chronic and very severe cases of liver failure." (PMID 40073124, 2025). "First, patients with hypoalbuminemia are more susceptible to fluid overload from albumin infusion, which may exacerbate pulmonary or cardiovascular complications." (PMID 40649163, 2025). "For the uncertainty of the clinical benefit of albumin in septic patients with hypoalbuminemia, we sought to clarify whether albumin infusion is associated with improved outcomes." (PMID 40649163, 2025). "For instance, the association between hypoalbuminemia and reduced muscle mass has been documented in various populations, indicating that decreased albumin levels may serve as a prognostic marker for sarcopenia." (PMID 40686817, 2025). "As for inflammation, it is linked to hypoalbuminemia; it can increase capillary permeability, leading to serum albumin crossing the capillary membrane, which may contribute to increases in the volume of the interstitial space." (PMID 40649163, 2025). "Additionally, hypoalbuminemia—a hallmark of cirrhosis—significantly impacts AG as albumin is a major unmeasured anion." (PMID 40938881, 2025). "Clinical observational studies have demonstrated that persistent hypoalbuminemia is associated with adverse outcomes in patients with sepsis, whereas normalization of serum albumin levels may indicate clinical improvement." (PMID 41180526, 2025). "Given the complications associated with hypoalbuminemia, albumin supplementation may be an important focus of patient management during critical illness." (PMID 40538723, 2025). "Notably, however, other studies have shown that the prevalence of hypoalbuminemia in patients with disease limits the diagnostic performance of albumin, restricting it to serving only as a surrogate marker for predicting survival." (PMID 40705791, 2025). "However, it is entirely possible that hypoalbuminemia can be caused by the loss of albumin due to long-term severe proteinuria, such as in nephrotic syndrome." (PMID 41375027, 2025). "High levels of serum CRP are associated with hypoalbuminemia, which may be due to decreased hepatic capacity to synthesize albumin as a result of increased expression of a range of inflammatory factors." (PMID 40309739, 2025). "Notably, significantly reduced albumin levels are detected in patients with concurrent pulmonary bacterial infections, as hypoalbuminemia is associated with bacterial infections and worse outcomes in patients with COVID-19." (PMID 41270012, 2025). "In addition, hypoalbuminemia at diagnosis was associated with a significant reduction in terms of OS compared to patients with a normal value of albumin at diagnosis (p < 0.001)." (PMID 39941726, 2025). "It remains unclear whether persistent or worsening hypoalbuminemia during hospital stay confers additional risk or if early correction of low albumin improves outcomes in TBI." (PMID 41226896, 2025). "Given albumin's role in lipoprotein metabolism, hypoalbuminemia secondary to increased enteric loss in dogs with PLE might alter the rate of hepatic protein (particularly albumin) and lipid synthesis, as well as albumin catabolism and urinary clearance." (PMID 40123416, 2025). "Studies have shown that hypoalbuminemia in ED patients may be associated with disease severity, which is attributed to suppressed albumin synthesis and accelerated consumption caused by abnormal liver metabolism or inflammatory responses." (PMID 40705791, 2025).
Hypoalbuminemia (continued). "Thus, albumin-deficient mice were more susceptible to mucormycosis, and severe hypoalbuminemia was associated with poor prognosis in patients with mucormycosis." (PMID 41003169, 2025). "However, while hypoalbuminemia is linked to poor outcomes, the potential benefits of albumin supplementation remain inconclusive, as recent studies have produced mixed results." (PMID 41428744, 2025). "In this single-center cohort of adults receiving maintenance HD, hypoalbuminemia (<3.5 g/dL) was strongly associated with greater healthcare utilization: patients with low albumin had a substantially higher probability of hospitalization and longer mean hospital stays." (PMID 41552166, 2025). "Notably, there was a steep rise in the risk at a serum albumin level of around 3.5 g/dL, corresponding to the cutoff level used to define hypoalbuminemia." (PMID 39728268, 2024). "In addition to hypocobalaminemia, ileal lesion severity is also reflected by hypoalbuminemia and intestinal lymphangiectasia, particularly in the ileum, has been linked to hypoalbuminemia (serum albumin concentration < 25 g/L)." (PMID 39238011, 2024). "Furthermore, albumin levels have been found to be decreased in patients with severe COVID-19, and such hypoalbuminemia has been demonstrated to be associated with increased mortality." (PMID 38584822, 2024). "Albumin supplementation may be another interesting option to counteract the hypercoagulable state and lower the thrombotic risk in cirrhotic patients with hypoalbuminemia." (PMID 39165413, 2024). "This study aims to investigate whether hypoalbuminemia, defined as serum albumin levels ≤35 g/L, is associated with mortality specifically attributed to cancer and/or vascular diseases." (PMID 39010980, 2024). "Previous studies have suggested that hypoalbuminemia is common in COVID-19 patients, and dynamic monitoring of serum albumin may be useful in evaluating the risk of reinfection with COVID-1955–58." (PMID 38992084, 2024). "Consequently, we recommend that clinicians adopt standardized protocols for managing preoperative serum albumin levels, highlighting the significant impact of hypoalbuminemia on inflammatory activity and predictive risk." (PMID 38420358, 2024). "We found that admission hypoalbuminemia was an independent predictor of increased 30-day readmission risk in elderly hip fracture patients, with a dose–response relationship between declining albumin levels and higher readmission incidence." (PMID 38528491, 2024). "The low albumin indicates hypoalbuminemia from protein loss." (PMID 39092327, 2024). "Additional intraoperative albumin supplementation may be necessary in patients with hypoalbuminemia since perioperative hypoalbuminemia has been proven to be independently associated with increased morbidity and mortality after cardiac operations." (PMID 38229019, 2024). "Firstly, transfusion may replenish plasma albumin levels, thereby correcting the low oncotic pressure and complications like edema and ascites that are associated with hypoalbuminemia." (PMID 38528491, 2024). "Albumin sequestration in ascitic fluid could be the cause of the association between high nitrite levels and hypoalbuminemia." (PMID 38396668, 2024). "The postoperative PNI value may be associated with hypoalbuminemia because serum albumin level is an important parameter in PNI." (PMID 39430095, 2024). "Furthermore, when hypoalbuminemia was categorized into mild and severe levels, the results also showed that lower albumin levels correlated with a higher risk of CIA (OR, 3.65; 95% CI, 2.77–4.76 for mild vs. OR, 5.10; 95% CI, 2.22–10.22 for severe)." (PMID 39723253, 2024). "Firstly, cancer patients may experience hypoalbuminemia due to the continuous consumption of nutrients, including albumin, by the tumor, leading to a deficiency of these essential nutrients in the body." (PMID 39687887, 2024).
Hypoalbuminemia (continued). "However, in the sensitivity analysis performed excluding other possible causes of hypoalbuminemia, the risk of early cardiovascular complications in patients with stroke was still associated with albumin levels." (PMID 38323429, 2024). "Consequently, we recommend proactive adjustment of albumin levels for patients with hypoalbuminemia to reduce the risk of CIA occurrence." (PMID 39723253, 2024). "Previous studies linked hypoalbuminemia with anemia across various populations, suggesting that decreased albumin levels may be associated with inflammatory processes, contributing to anemia." (PMID 39408389, 2024). "Serum albumin plays a neuroprotective role, and hypoalbuminemia is linked to poor outcomes." (PMID 39347246, 2024). "Given that zinc is bound to albumin, hypoalbuminemia may mimic zinc deficiency owing to decreased zinc-binding capacity." (PMID 39189285, 2024). "The risk of death for cats with normal albumin concentration vs hypoalbuminemia approached statistical significance, but a type II error may have affected the outcome." (PMID 38517293, 2024). "Multivariate analysis showed that the serum albumin level was the only variable significantly associated with all lipid measurements and thus, in the case of hypoalbuminemia, with an atherogenic constellation of lipids, i.e., higher levels of CHOL, LDL-C, and TG and lower HDL-C." (PMID 38720111, 2024). "In addition, patients with overt HE and severe hypoalbuminemia, where serum albumin was ≤22.8 g/L, were more likely to die from HE‐associated mortality." (PMID 39301299, 2024). "If hypoalbuminemia is confirmed as an independent risk factor, therapeutic interventions such as human serum albumin infusion could be employed to reduce the incidence and severity of CIA." (PMID 39723253, 2024). "Furthermore, systemic inflammatory markers like C-reactive protein, interleukin-1, and the tumor necrosis factor are intricately linked with hypoalbuminemia due to their role in inhibiting albumin synthesis." (PMID 38473396, 2024). "Serum albumin level is often used to assess patient nutritional condition, although hypoalbuminemia may also be linked to inflammation." (PMID 37234246, 2023). "In some patients, an increase in albumin levels at the onset of PD may reduce the risk of peritonitis due to hypoalbuminemia." (PMID 36762995, 2023). "Since chronic inflammation can cause hypoalbuminemia, it might also underlie the inverse association between serum albumin and height loss." (PMID 37700384, 2023). "Lower albumin and prealbumin levels may indicate poor preoperative nutritional status, and previous studies have reported that hypoalbuminemia is a risk factor for transfusion." (PMID 36597109, 2023). "This study demonstrated that albumin infusions could reduce the risk of mortality in hypoalbuminemia patients with SAP." (PMID 37277756, 2023). "Additionally, pronounced inflammatory response induces hypoalbuminemia, and the aging process, itself has been linked to lower levels of albumin." (PMID 37213604, 2023). "There were 3 cases of hypoalbuminemia after the operation, which may have been caused by preoperative fasting due to pain, but all of them resolved after human albumin infusion and moderate nutritional support." (PMID 38110402, 2023). "Therefore, this study found that hypoalbuminemia is an independent risk factor for intracranial atherosclerosis, and albumin, as the main antioxidant in the human body." (PMID 37210474, 2023). "Hyperbilirubinemia, which is caused by the lysis of hepatocytes and is indicative of intense inflammatory responses, and hypoalbuminemia are more representative of increased capillary permeability associated with systemic vasculitis that leads to a higher leakage of serum albumin." (PMID 36129563, 2023).
Hypoalbuminemia (continued). "Decreased albumin synthesis and increased catabolism after oxidation is observed in liver disease and our dataset agrees with recent publications showing an association of hypoalbuminemia with poor outcome in critically ill population including COVID-19." (PMID 37641126, 2023). "Hypoalbuminemia may be the result of decreased production of albumin or increased loss of albumin via the kidneys, gastrointestinal tract, skin, or extravascular space." (PMID 37892441, 2023). "Our study found a clear and significant association between the presence of hypoalbuminemia upon admission and increased odds of developing UTIs in elderly hip fracture patients and a dose–response relationship was observed, as lower albumin levels were associated with a higher risk of infection." (PMID 37838687, 2023). "Similarly, hypoalbuminemia can be caused by renal loss, and studies have indicated that low serum albumin significantly predicts DVT occurrence in nephrotic syndrome." (PMID 37653556, 2023). "Both the elderly and the female sex are associated with a decreased lean body mass, reduced total body water, and a decreased serum albumin concentration (hypoalbuminemia), and these factors are associated with an increased risk of the elevation of free drug fraction." (PMID 36836682, 2023). "Further prospective studies with a standardized study and infusion protocol as well as standardized assessmet of the illness severty and cause of hypoalbuminemia are required to assess the effect of the amino acid infusion on albumin and total protein concentration." (PMID 37342623, 2023). "We consider that hypoalbuminemia may be a reflection of trauma severity which is associated with increased albumin catabolism." (PMID 37370139, 2023). "The hypoalbuminemia detected in our patients could be explained because the inflammation caused by COVID-19 involves a degradation of circulating albumin." (PMID 37873785, 2023). "In CD patients, the higher the albumin levels, the higher the clinical remission rate after a dose escalation of infliximab; while hypoalbuminemia is associated with a worse outcome, a greater risk of relapse and interrupting anti-TNF therapy for albumin serum levels < 3.5 g/dL (p = 0.0274)." (PMID 37686856, 2023). "One study used the data as a continuous variable, and four studies defined hypoalbuminemia as a common cutoff value (serum albumin level ≤3.5 g/dL), and a significant association with all-cause mortality was found in all these studies (range of HR: 2.497–4.78)." (PMID 38003795, 2023). "Inflammation was associated with increased catabolism and decreased albumin synthesis, and hypoalbuminemia may increase blood viscosity and disrupt endothelial function." (PMID 37803270, 2023). "Albumin is a significant biomarker of liver function, hypoalbuminemia could be caused by the liver producing less, losing more, or increasing proteolysis and clearance." (PMID 36655071, 2023). "Hence, it was crucial to monitor albumin and hemoglobin levels in HD patients and take appropriate measures to prevent and manage anemia as well as hypoalbuminemia, to reduce the risk of complications during the COVID-19 pandemic." (PMID 37305144, 2023). "Emphasizing the importance of albumin, a recent retrospective study on 114 COVID-19 patients have demonstrated that albumin infusion to ICU patients with hypoalbuminemia was associated with shorter hospitalization, prolonged survival, and enhancement in some of the laboratory markers." (PMID 37497238, 2023). "Albumin loss by extravasation into the inflamed nerves is a possible cause of hypoalbuminemia, because in severe cases (axonal type) cerebrospinal fluid protein rises to more than one gram per liter with similar extravasation throughout the peripheral nervous system." (PMID 37634022, 2023).
Hypoalbuminemia (continued). "Hypoalbuminemia is associated with the acquisition and severity of infectious diseases due to the fact that the intact innate and adaptive immune response is largely dependent on albumin." (PMID 38186651, 2023). "Similarly, in adults, hypoalbuminemia is associated with severe COVID-19 and researchers have found an inverse relationship between the levels of albumin and the risk of death in COVID-19 patients." (PMID 37744432, 2023). "Therefore, perioperative hypoalbuminemia is attributed to several factors including albumin loss, protein catabolism, and inflammatory cytokines." (PMID 35971104, 2022). "Hypoalbuminemia was associated with a mortality of 47%; normal albumin, only 14%." (PMID 35268297, 2022). "Also, low serum albumin and volume overload contribute to an increased risk of death and hypoalbuminemia itself can affect fluid retention in ESRD patients." (PMID 35204349, 2022). "The advantage of the albumin loss endurance in our hypothesis makes the preoperative albumin value ≥40 g/L a protective factor for postoperative hypoalbuminemia." (PMID 35571899, 2022). "However, we found that postoperative albumin infusion was a risk factor for PPLOS in patients with preoperative hypoalbuminemia and in those with a longer duration of surgery." (PMID 36566186, 2022). "In this spline analysis, we observed that an increase in preoperative serum albumin concentration by 1 g/dL was associated with decreased odds of death among patients with preoperative hypoalbuminemia (≤3.4 g/dL), even after controlling for relevant clinical covariates." (PMID 36362771, 2022). "Given that hypoalbuminemia is also a recurrent finding in chronic disease, data from predominantly community-acquired sepsis showed that hypoalbuminemia is related to infection and that albumin could act as an independent risk parameter." (PMID 35906231, 2022). "Hypoalbuminemia can be caused by low energy supply, increased loss of serum albumin, decreased liver synthesis, increased catabolism, and distribution failure of serum albumin." (PMID 36579497, 2022). "Although acute hypoalbuminemia may need to be rapidly corrected by albumin and furosemide to manage potential adverse events, the treatment of chronic hypoalbuminemia requires focusing on the underlying causes." (PMID 35770216, 2022). "It was important to find out whether serum albumin is an independent prognostic marker, or part of other disorders known to be associated with hypoalbuminemia (Hypoalbuminemia-associated disorders, HAD)." (PMID 35268297, 2022). "Hypoalbuminemia may be caused by inflammation, hepatocyte damage, decreased albumin synthesis, the dietary insufficiency of amino acids or increased excretion of albumin." (PMID 36292245, 2022). "Previous studies have reported that systemic inflammation can lead to an increase in capillary permeability, which has been shown to cause the release of serum albumin into the interstitial space, which is why most patients presented with hypoalbuminemia and high levels of liver enzymes." (PMID 35774706, 2022). "We proposed a hypothesis and for the convenience to state it, we induced the conception of albumin loss endurance, which means the difference value between the preoperative actual albumin value and the diagnostic value of hypoalbuminemia of 35 g/L." (PMID 35571899, 2022). "Although albumin is initially considered as a marker reflecting nutritional condition, it is negatively regulated by the acute phase reactant and the association between hypoalbuminemia and septic failure after joint replacement has been discovered." (PMID 34991649, 2022). "Similarly, aggravated adverse reactions to diazepam were reported in hypoalbuminemia and low serum albumin was associated with longer methotrexate clearance." (PMID 35962801, 2022). "Thus, hypoalbuminemia develops when renal albumin loss (albuminuria, combined with tubular albumin reclaiming and degradation) surpasses undermined hepatic albumin synthesis." (PMID 36139492, 2022).